IGF2BP1 (insulin like growth factor 2 mRNA binding protein 1)
Diseases named in the same sentence as IGF2BP1 in open-access papers (continued):
Sharing a sentence is not in itself a finding about the gene and the disease.
osteosarcoma (continued). "In recent studies, we identified various novel candidate target transcripts of IGF2BP1 using the selective stabilization of mRNAs by the protein during cellular stress as a screening criterion in osteosarcoma-derived U2OS cells." (PMID 23677615, 2013). "Similarly, Zhou and Xu showed that BMSC-derived exosomes inhibited osteosarcoma progression by transferring miR-1913 or miR-150 to osteosarcoma cells to suppress NRSN2 or IGF2BP1 expression, respectively." (PMID 37377390, 2023). "Moreover, MSC-derived EVs carrying miR-150 reduce proliferation and migration of osteosarcoma cells by targeting IGF2BP1 (Insulin-like Growth Factor-2 mRNA-Binding Protein 1)." (PMID 34830463, 2021). "In addition to IGF2BP1, let-7b targets a variety of oncogenes and has been proposed to act as a tumor suppressor in human osteosarcoma by targeting insulin-like growth factor-1 receptor." (PMID 33937369, 2021). "The newly identified miR-150/IGF2BP1 axis might be a novel potential therapeutic target for osteosarcoma treatment." (PMID 30220021, 2019). "Importantly, the expression levels of IGF2BP1 mRNA in osteosarcoma tissues were positively correlated with that of IGF2BP1 protein in osteosarcoma tissues (Spearman correlation r = 0.49, P = 0.03)." (PMID 30220021, 2019). "Moreover, miR-150, IGF2BP1 and combined miR-150/IGF2BP1 expressions were all identified as independent prognostic factors for overall and disease-free survivals of osteosarcoma patients (all P < 0.05)." (PMID 30220021, 2019). "Previous study revealed that microRNA (miR)-150 might function as a tumor suppressor in osteosarcoma partially by targeting Insulin-Like Growth Factor 2 mRNA-Binding Protein 1 (IGF2BP1)." (PMID 30220021, 2019). "Among 100 patients with osteosarcomas, 32 (32.00%), 20 (20.00%), 19 (19.00%) and 29 (29.00%) were respectively in miR-150-low/IGF2BP1-high, miR-150-low/IGF2BP1-low, miR-150-high/IGF2BP1-high, miR-150-high/IGF2BP1-low groups." (PMID 30220021, 2019). "Moreover, miR-150 suppressed tumor growth in an osteosarcoma xenograft mouse model via repression of IGF2BP1." (PMID 30558204, 2018). "In osteosarcoma, miR-150 functions as a tumor suppressor partially by targeting IGF2BP1." (PMID 26871477, 2016). "METTL3/m6A/IGF2BP1-mediated stabilization of melanoma cell adhesion molecule (MCAM) and zinc-fingers and homeoboxes 2 (Zhx2) mRNA suppressed apoptosis of osteosarcoma cells and RCC cells." (PMID 40584294, 2025). "Up-regulation of IGF2BP1 is also closely related to poor overall survival and high tumor grades in RCC and osteosarcomas, as well as with short disease-free survival and overall survival in intrahepatic cholangiocarcinoma." (PMID 40584294, 2025). "Exo-miR-150 targets IGF2BP1, Exo-miR-195 targets KIF4A, Exo-miR-206 targets NRSN2, and RGD-Exo targets Rad18, along with other pathways that impede the evolution of osteosarcoma." (PMID 39605980, 2024). "To address this problem, we firstly detected the expression levels of miR-150, and IGF2BP1 mRNA and protein in 20 osteosarcoma and matched adjacent noncancerous tissues by quantitative real-time PCR and western blot analyses, respectively." (PMID 30220021, 2019). "As a result, miR-150 expression was significantly decreased, while IGF2BP1 mRNA and protein expression were dramatically increased in osteosarcoma tissues compared to matched adjacent noncancerous tissues (all P < 0.001)." (PMID 30220021, 2019). "At first, expression levels of miR-150, and IGF2BP1 mRNA and protein in 20 osteosarcoma and matched adjacent noncancerous tissues were respectively detected by quantitative real-time PCR and western blot analyses." (PMID 30220021, 2019).
gastric cancer (18 papers, 2018 to 2026). A primary or metastatic malignant neoplasm involving the stomach. "Enhanced GHET1 expression can contribute to gastric carcinoma cell proliferation and tumor growth in vitro and in vivo by physically associating with IGF2BP1 and increasing the physical interaction of IGF2BP1 with c-Myc mRNA, consequently enhancing c-Myc mRNA stability and expression." (PMID 29954406, 2018). "IGF2BP1 exerts tumor-suppressive effects in gastric cancer development by suppressing MYC expression through an m6A-mediated mechanism." (PMID 40986143, 2025). "In terms of overcoming drug resistance, the interaction of phosphoglycerate dehydrogenase (PHGDH) with IGF2BP1 can facilitate the m6A-dependent stabilization of transcription factor 7 Like 2 (TCF7L2) mRNA to confer multidrug resistance in gastric cancer." (PMID 40986143, 2025). "For example, in gastric cancer, m6A reader IGF2BP1 upregulated in gastric cancer tissue and acted as a predictor of poor prognosis for gastric cancer patients and IGF2BP1 directly interacts with c-MYC mRNA via m6A-dependent manner to stabilize its stability." (PMID 36691477, 2023). "According to previous study, GHET1 interacted with IGF2BP1 to stabilize c-Myc mRNA so as to promote gastric cancer." (PMID 31682716, 2020). "Meanwhile, a positive correlation between TRPM2-AS and IGF2BP1 (R = 0.5415, P = 0.01) was found in 20 paired gastric cancer tissues, as well as between FOXM1 and TRPM2-AS (R = 0.5056, P = 0.02)." (PMID 32123162, 2020). "Importantly, IGF2BP1 has been reported to modulate tumor progression by stabilizing target lncRNAs in gastric cancer." (PMID 41208889, 2025). "For instance, in gastric cancer, IGF2BP1 overexpression augments the proliferation of co-cultured gastric cancer cells, and mitigates the CD8+ T cells mediated anti-tumor response, including IFN-γ secretion, surface PD-L1 level, and cytotoxicity of CD8+ T cells." (PMID 39606242, 2024). "In conclusion, these results suggested there may exist an axis between TRPM2-AS, miR-612 and IGF2BP1 which involved in the tumorigenesis and aggressiveness of gastric cancer." (PMID 32123162, 2020). "Previous study has demonstrated in gastric cancer that GHET1 could interact with IGF2BP1, a member of IGF-2 binding proteins, to stabilize c-Myc mRNA." (PMID 31682716, 2020). "IGF2BP1 mediated the stability of NRF2 mRNA to reduce the antitumor immunity and ferroptosis of gastric cancer." (PMID 39606242, 2024). "Gastric carcinoma high expressed transcript (GHET1) interacts with IGF2 mRNA binding protein 1 (IGF2BP1), which enhances the interaction between IGF2BP1 and c-Myc and increases the expression of c-Myc, thereby promoting cell proliferation." (PMID 35511773, 2022). "In gastric cancer, the up-regulation of GHET1 promotes tumor cell proliferation in vitro and in vivo by physically binding to IGF2BP1, thereby enhancing the interaction between c-Myc mRNA and IGF2BP1; this can enhance the stability of c-Myc mRNA." (PMID 32280301, 2020). "In gastric cancer, the interaction of PHGDH with insulin-like growth factor 2 mRNA binding protein 1 (IGF2BP1) stabilizes TCF7L2 mRNA and increases its expression, resulting in the activation of the Wnt/β-catenin signaling pathway thereby contributing to multi-drug resistance." (PMID 40640948, 2025). "Since the effect of IGF2BP1 on gastric cancer has never been reported before, so we transfected IGF2BP1-targeting siRNA into SGC7901 and MGC803 cells to determine whether IGF2BP1 involves in GC cell proliferation and metastasis." (PMID 32123162, 2020).
colon cancer (16 papers, 2015 to 2025). "IGF2BP1 loss was found to inhibit the expression of K-Ras and Cdc34, the let-7 repressor Lin-28B, and c-Myc, concomitantly depress anchorage-independent growth and colon cancer cell proliferation, and trigger caspase-mediated cell death." (PMID 29954406, 2018). "Overexpression of IGF2BP1 is seen in multiple epithelial tumors such as breast, pancreatic, and colon cancers." (PMID 38571491, 2024). "In colon cancer, upregulation of IGF2BP1 suppresses the CD8+ T-cells mediated antitumor immunity through reducing the tumor cytotoxicity and enhancing the target PD-L1 mRNA stability." (PMID 39606242, 2024). "The detection of serum autoantibodies to IGF2BP1 in esophageal squamous cell carcinoma and IGF2BP1/3 in colon cancer contributes to identifying patients with cancer, and when combined with other TAAs, achieves greater sensitivity and specificity for diagnosis." (PMID 37280679, 2023). "Its deletion downregulates k-RAS expression downstream of β-catenin and simultaneously inhibits colon cancer cell proliferation, whereas IGF2BP1 overexpression increases c-MYC and K-RAS expression and promotes colon cancer cell proliferation." (PMID 36844874, 2023). "They indicated that IGF2BP1, interrelated with c-Myc, acts upstream of K-Ras to promote survival, which was a novel mechanism important in colon cancer pathogenesis." (PMID 34203267, 2021). "The oncogenic insulin-like growth factor 2 mRNA-binding protein 1 (IMP1) has been previously shown to regulate KRAS mRNA expression in colon cancer cells, possibly through its ability to bind to the KRAS transcript." (PMID 32369483, 2020). "During the process, c-Myc and IGF2BP1 constitute a potential feedback mechanism to reciprocally regulate expression of each other in colon cancer." (PMID 29954406, 2018). "An oncogenic function of HMGA1 and IGF2BP1 has been reported in other cancers, including colon cancer, with evidence that both factors enhance tumorigenesis." (PMID 26244988, 2015). "Similarly, in a colon cancer mouse model, it was observed that stromal expression of IGF2BP1 was critical for the inhibition of the growth of colon cancer." (PMID 38571491, 2024). "IGF2BP1 facilitates the glycolysis of colon cancer by binding and stabilising the LDHA, which could promote the lactic acid accumulation and acidic TME production." (PMID 36747239, 2023). "Since these genes are directly regulated by IGF2BP1, we investigated whether there is a direct correlation between these signature genes and IGF2BP1 in colon cancer patients." (PMID 37829185, 2023). "For example, overexpression of miR-873 could reduce proliferation, migration, and invasion of glioblastoma pleomorphic cells by regulating IGF2BP1 expression, such as in colon cancer." (PMID 36147635, 2022). "Additionally, our findings highlight IGF2BP1 as a possible therapeutic target and a prognostic marker for colon cancer, which could be utilized to improve accuracy and even reduce cost of colon cancer detection and treatment." (PMID 37829185, 2023). "Additionally, IGF2BP1 silencing could increase the effectiveness of hyperthermia therapy in colon cancer cells." (PMID 35918761, 2022). "Further, matching the IGF2BP1 interactome data with transcriptomic data, we have found 17 common genes, including MGAT5 and MET, which showed a higher degree of expression in colon tumors analyzed from the TCGA database." (PMID 37829185, 2023). "For example, the deletion of insulin-like growth factor 2 mRNA binding protein 1 (IMP1) can promote the occurrence and development of colon tumor microenvironment." (PMID 34568328, 2021). "Further analysis indicated a strong positive correlation between IGF2BP1 and YTHDF1 in colon cancer." (PMID 33500720, 2021). "Consistent with the results of the current study, IGF2BP1 could bind with LDHA 3′-UTR, thus resulting in enhanced LDHA mRNA stability and increased glycolysis in colon cancer cells." (PMID 35918761, 2022).
colon cancer (continued). "It was found that the expression of IGF2BP1 (probe: 227377_at*) was not altered in non-responders to any chemotherapy (5-fluorouracil, oxaliplatin, bevacizumab, irinotecan, and capecitabine) compared to 91 responder colon cancer patients." (PMID 34203267, 2021). "Overall, this study highlights the complex and context-dependent regulation of Wnt/β-catenin signaling target genes by IGF2BP1 in non-transformed and CRC cells and identifies potential targets for colon cancer treatment." (PMID 37829185, 2023).
endometrial cancer (16 papers, 2021 to 2025). Primary or metastatic malignant neoplasm involving the endometrium (mucous membrane that lines the endometrial cavity). "Previous studies, primarily based on Western cohorts, have associated high IGF2BP1 expression with poor prognosis and aggressive tumor behavior in endometrial cancer (EC)." (PMID 41210679, 2025). "Furthermore, high expression of IGF2BP1 was associated with poor prognosis in endometrial cancer patients." (PMID 36894952, 2023). "Intriguingly, a recent study highlighted the important role of IGF2BP1 in m6A-mediated PEG10 upregulation in endometrial cancer, reinforcing evidence for the m6A-IGF2BPs-PEG10 regulatory axis identified in our study." (PMID 39438075, 2024). "Increased expression of IGF2BP1 in endometrial cancer (EC) can promote cell proliferation and regulate tumor progression." (PMID 39028290, 2024). "In endometrial cancer, IGF2BP1 regulates cell cycle and promotes cell proliferation through employing the cofactor PABPC1 and stabilizing m6A-modified PEG10 mRNA." (PMID 37280679, 2023). "In endometrial cancer, IGF2BP1 is a direct downstream target of peptidylarginine deiminase II (PADI2) that is required for endometrial cancer progression, and IGF2BP1 binds to the m6A sites of oncogenic SOX2 and prevents its mRNA degradation." (PMID 35541906, 2022). "Furthermore, in CRC, cervical cancer, and endometrial cancer, m6A/IGF2BP1-mediated mRNA stabilizations of DEAD-box helicase 27 (DDX27), BDNF, and SYVN1 are also vital for tumor cells to enhance epithelial–mesenchymal transition." (PMID 40584294, 2025). "For example, one study in endometrial cancer demonstrated that IGF2BP1 was able to enhance the mRNA stability of paternally expressed gene 10 by recognizing m6A sites within it, thereby accelerating the cell cycle of endometrial cancer cells through downstream signaling." (PMID 36249006, 2022). "However, it is unclear which genes IGF2BP1 targets to identify m6A sites and what are their respective functions in endometrial cancer (EC)." (PMID 33391523, 2021). "These analyses indicated that IGF2BP1 may be the top candidate target for PADI2 in endometrial carcinoma cells." (PMID 33747724, 2021). "While this interaction remains unexplored in endometrial cancer, the mechanistic insights from other systems provide a strong rationale for investigating whether IGF2BP1 similarly regulates PKM2 expression and contributes to metabolic reprogramming and tumor progression in this context." (PMID 41210679, 2025). "Another study found that the m6A reader IGF2BP1 enhanced PEG10 expression and promoted endometrial cancer cell proliferation by recognizing the m6A site in PEG10 mRNA." (PMID 36894952, 2023). "IGF2BP1 can bind to the m6A site of Sox2 3’-UTR to inhibit its degradation, thus promoting the progression of endometrial cancer." (PMID 35022030, 2022). "Recent studies revealed that IGF2BP1 bound to the 3’UTR m6A site of SOX2 mRNA and inhibited the degradation of SOX2 mRNA, which in turn led to the proliferation and metastasis of endometrial cancer cells." (PMID 35945641, 2022). "Overexpression of IGF2BP1 stabilizes PEG10 mRNA in an m6A-dependent manner and promotes endometrial cancer progression." (PMID 36299451, 2022). "IGF2BP1 recognizes the m6A site on PEG10 and SOX2 mRNAs and increases the expression of these mRNAs by enhancing their stability, promoting the malignant progression of endometrial cancer." (PMID 35945641, 2022). "In endometrial cancer, PADI2 (peptide arginine deaminase II) can convert arginine residues to citrulline, participates in the regulation of amino acid metabolism, catalyzes the citrullination of MEK1-R113/189, promotes the phosphorylation of ERK1/2, and activates the expression of IGF2BP1." (PMID 35022030, 2022).
endometrial cancer (continued). "In addition, it has been reported that IGF2BP1 is involved in the guanylation of arginine in endometrial cancer, and the PADI2/MEK1/ERK signalling pathway-mediated dysregulation of IGF2BP1 leads to the upregulation of SOX2 expression, resulting in the malignancy of endometrial cancer cells." (PMID 36894952, 2023).
glioma (15 papers, 2019 to 2025). A benign or malignant brain and spinal cord tumor that arises from glial cells (astrocytes, oligodendrocytes, ependymal cells). "Multiple long non-coding and micro RNAs targeting IGF2BP1, 2 and 3 have been implicated in glioma, using both patient-derived cell lines and xenograft models." (PMID 37444417, 2023). "IGF2BP1 has been shown to be upregulated in glioma and is associated with increased proliferation and invasiveness." (PMID 37444417, 2023). "IGF2BP1 is upregulated in human glioma tissue, which is associated with cell proliferation, migration, invasion, and cancer progression." (PMID 35625706, 2022). "Interestingly, IGF2BP1 is upregulated in human glioma tissue and associated with cell proliferation, migration, invasion, and tumor progression." (PMID 36139694, 2022). "Other studies have demonstrated that the expression of the lncRNA LINC00689 is upregulated in glioma, leading to increased expression of IGF2BP1 via the inhibition of miR-526b-3p." (PMID 40469294, 2025). "Long non-coding RNAs (lncRNAs) can serve as promising targets for treating gliomas, with IGF2BP1 playing an important role in the inhibition of glioma." (PMID 38072944, 2023). "For instance, Zhan and his group reported that LINC00689 expressions were distinctly increased in glioma, and its silence suppressed the proliferation and metastasis of glioma cells via mediation of miR-526b/IGF2BP1." (PMID 35251374, 2022). "Some non-coding RNAs, including miR-4500, miR-837, miR-506, miR-513, Lnc-THOR, and LINC00689, promote tumorigenesis in glioma through targeting IGF2BP1." (PMID 35625706, 2022). "The RIP results show that MAGEA6 mRNA directly binds to the IGF2BP1 protein in A172 cells and the primary glioma cells." (PMID 31727877, 2019). "miR-4500 inhibits the progression of human glioma by binding to IGF2BP1." (PMID 37964279, 2023). "Furthermore, miR-4500 downregulates the level of IGF2BP1 and its downstream factors (Gli1, IGF2 and c-Myc), thereby suppressing the proliferation, migration, and invasion of human glioma cells through targeting IGF2BP1 mRNA 3'-UTR." (PMID 38072944, 2023). "Besides Lnc-THOR, other non-coding RNAs (i.e., miR- 4500, miR-837, miR-506, and LINC00689) have been reported to promote tumorigenesis in gliomas through targeting IGF2BP1." (PMID 36139694, 2022). "miR-506 can also inhibit the proliferation of glioma through targeting IGF2BP1 gene." (PMID 32639004, 2020). "We show that Lnc-THOR directly binds to IGF2BP1 in established and primary human glioma cells." (PMID 31727877, 2019). "Moreover, CRISPR/Cas9-induced IGF2BP1 knockout activated MAGEA6-AMPK signaling as well, causing A172 glioma cell apoptosis." (PMID 31727877, 2019). "In addition, the RIP assay results show again the direct binding between Lnc-THOR and the IGF2BP1 protein in A172 cells and the primary human glioma cells." (PMID 31727877, 2019). "Similarly, miR-4500 also targets IGF2BP1 to inhibit the development of gliomas." (PMID 40469294, 2025). "Therefore, IGF2BP1 inhibitors may also be promising small molecule inhibitors for glioma treatment in the future." (PMID 35625706, 2022). "Similar to IGF2BP1, IGF2BP3 is a carcinogenic protein that significantly promotes the progression of glioma." (PMID 40469294, 2025). "For example, miR-526b-3p can suppress IGF2BP1, thereby inhibiting the MAPK pathway and reducing the incidence of gliomas." (PMID 40469294, 2025). "The Insulin-like Growth Factor 2 mRNA-Binding Proteins (IGF2BP) family, comprising IGF2BP1, IGF2BP2, and IGF2BP3, plays a crucial role in glioma development and response to treatment." (PMID 38474421, 2024). "The IGF2BP1 knock-out induced by CRISPR/Cas9 also activated MAGEA6-AMPK signaling, leading to the apoptosis of glioma cells (A172)." (PMID 36672345, 2023).